RNY4P25 (RNY4 pseudogene 25)
Gene: Miscellaneous RNA gene on chromosome 1 (151,439,000 to 151,439,095, forward strand). Ensembl gene ENSG00000238711.
Homologues: Orthologues: chimpanzee Y_RNA (99% identical), guinea pig Y_RNA (88% identical). Paralogues in human: RNY4 (91% identical), RNY4P6 (90% identical), RNY4P7 (89% identical), Y_RNA (89% identical), RNY4P10 (88% identical), RNY4P19 (88% identical), Y_RNA (88% identical), RNY4P27 (86% identical), RNY4P13 (85% identical), RNY4P14 (85% identical), RNY4P23 (85% identical), RNY4P24 (85% identical), and 87 more.
Diseases named in the same sentence as RNY4P25 in open-access papers:
RNY4P25 is named in the same sentence as 1 disease in open-access papers, as found by Europe PMC text mining. Sharing a sentence is not in itself a finding about the gene and the disease. The quoted sentences say what the papers report.
melanoma (2 papers, 2020 to 2023). A malignant, usually aggressive tumor composed of atypical, neoplastic melanocytes. "RNY3P1, RNY4P1, and RNY4P25 show significantly higher expression in stage 0 human melanoma than at more advanced stages." (PMID 37835660, 2023).